CD4 (CD4 molecule)
Diseases named in the same sentence as CD4 in open-access papers (continued):
Sharing a sentence is not in itself a finding about the gene and the disease.
AIDS (continued). "Robust CD4+ T cell responses to these epitopes may have conferred some protective immunity and prevented progression to AIDS for 20 yr." (PMID 37058141, 2023). "In addition, the frequencies of pTfh in p24+ cells were also inversely correlated with the CD4 count, supporting the idea that productively infected cells are less likely to be pTfh cells during AIDS." (PMID 38420260, 2023). "However, an important proportion of HIV/AIDS patients, about 8-42%, persistently maintain low CD4+ T cell counts despite continuous virological suppression after at least two years of ART." (PMID 37205108, 2023). "Using a similar definition (AIDS or World Health Organisation (WHO) stage 3 or 4 HIV/AIDS, or had a CD4 cell count <200 cells/mm3 at the time of diagnosis), a large study of 528,230 Chinese HIV PLWH found only 34% of cases between 2006 and 2014 to be late presenters." (PMID 37351535, 2023). "Another one of the strengths of this study may be the evaluation of therelated OC predisposing factors, such as CD4+ T-cell count, in the HIV/AIDS population." (PMID 38375522, 2023). "In addition to the benefit of being a point-of-care test, in Brazil, the cost–benefit of LFA is even higher than the CRAG-latex in people living with HIV/AIDS (PLHA) with CD4 ≤ 200 cells/μL." (PMID 36547617, 2022). "Cryptococcal meningitis is a fungal infection of the CNS, generally thought of as an opportunistic infection in those with T-cell immunodeficiencies including AIDS (usually with a CD4 count of less than 100), chronic steroid use, hematological malignancies, and transplant recipients." (PMID 36072174, 2022). "How exactly low CD4+ cell count of people diagnosed with AIDS (stage 4) at onset of COVID-19 disease could contribute to disease progression remains unclear." (PMID 34843064, 2022). "Other AIDS-defining opportunistic pathogens that resurface at low CD4+ counts (<200/mm3) may be potential confounders, possibly contributing to the sumoylation loss in vivo." (PMID 35181598, 2022). "Recent studies in the context of HIV mono-infection have shown that higher levels of CXCL10 in the blood were associated with more rapid HIV disease progression and lower CD4+ T cell counts, in addition to being a reliable marker for predicting the progression to AIDS." (PMID 35916523, 2022). "From 408 mothers followed up at two HIV-AIDS RCs, Constanta and Craiova inRomania, the most important clinical and biological risk factors associated with increased MTCT of HIV are represented by anemia, CD4 level, and HIV patient stage." (PMID 35208597, 2022). "Therefore, physicians should consider microsporidiosis in HIV/AIDS patients with such low CD4 cell counts, particularly diarrheic patients." (PMID 34983416, 2022). "Furthermore, the CD4+ T cell count was below 150 cells/μL in all nine Cryptosporidium-infected MSM HIV/AIDS individuals." (PMID 36067140, 2022). "The present patient had a history of AIDS, with a low level of CD4 T-lymphocytes." (PMID 36076296, 2022). "Thus, we suggest that LYMPH, RBC, and HGB can predict the immune status of HIV/AIDS patients together with CD4+ T cell count." (PMID 36067140, 2022). "Also, CD4+ T-cell depletion (<20 CD4+ T-cell counts) as found in IC persons, including persons living with HIV/AIDS, has been determined to increase the risk of giving rise to SARS-CoV-2 resistance mutations." (PMID 36226173, 2022). "Median nadir CD4+ count was 287 cells/mm3, and 13% had a previous AIDS diagnosis." (PMID 35916394, 2022). "In an Italian study, a third dose mRNA booster of either BNT162B2 or mRNA-1273 > 28 days following a complete mRNA vaccination course was found to strongly boost humoral responses in PLWH with advanced disease (CD4+ T cell count <200 cells/μl and/or previous AIDS)." (PMID 36846557, 2022). "It was gradually recognized that CD4+ T cell count does not reflect immune activation and risk of non-AIDS-defined events, despite its crucial role in monitoring immune recovery." (PMID 35444646, 2022).
AIDS (continued). "However, CXCR4 use was not identified from later time points in any of the four individuals, including the individual who had developed AIDS and later presented with very low T-cell levels (CD4+ T-cell count = 60 cells/μL, CD4% = 6)." (PMID 36366545, 2022). "In this comparison of a standard RDA multivitamin to a high-dose multivitamin with antioxidants, we did not observe a significant change in HIV-disease progression as measured by CD4 T lymphocyte decline below 350 cells/μL, emergence of documented AIDS-defining illness, start of ART, or death." (PMID 35834528, 2022). "Furthermore, 30.9% (80/259) had AIDS (i.e., CD4 < 200 cells/mm3), while 15.1% (39/259) had severe immunosuppression (i.e., CD4 < 100 cells/mm3)." (PMID 35743539, 2022). "It is time to contend for those with low CD4 counts who are most likely to die of AIDS." (PMID 35136596, 2022). "If untreated, HIV-1 infection leads to a decrease in the CD4 T cell count, leading to AIDS." (PMID 35335016, 2022). "As the vast majority of cases of aspergillosis in patients with HIV/AIDS in this systematic review had a CD4 <50 cells/mm3, healthcare staff need to consider the possibility of aspergillosis in HIV patients with low CD4 counts (<100 cells/uL) and pulmonary lesions." (PMID 36354898, 2022). "This conclusion is supported by studies which have suggested that CD4+ cell count gains < 100 cells/μl/year can be used to identify patients at risk of hard endpoints such as AIDS, serious non-AIDS events, and death." (PMID 36357837, 2022). "In the second cohort, we observed that increases in peripheral blood GrimAge residuals for those PLWH with airflow obstruction can occur early on in HIV infection, prior to the reduction in CD4 counts and the development of opportunistic infections and AIDS-related complications." (PMID 35944348, 2022). "CD95 mediates apoptosis-induced depletion of CD4+ T cell in AIDS." (PMID 35203323, 2022). "The study of HIV/AIDS has provided an unprecedented platform to understand our immunity, specifically the role of CD4 T-cells in eukaryotic vs. prokaryotic immunity against viral infections, and in prevention as well as cure, including the vaccination (immunization)." (PMID 35632825, 2022). "Overview of the role of Tr1 and IL-10-producing CD4+ T cells in AIDs and IBD." (PMID 36389662, 2022). "Immune-based therapy for COVID-19, while potentially lifesaving, may have potential for harm in certain immunocompromised patients, such as PWH with CD4 < 200 cells/mm3 or AIDS." (PMID 35148782, 2022). "The persistence of high levels of circulating CD8+ T-cells or a low CD4/CD8 ratio translates into immunosenescence and heightened immune activation and has been associated with an excess risk of non-AIDS comorbidities and higher all-cause mortality in people living with HIV (PLHIV) receiving ART." (PMID 35432298, 2022). "Median CD4 nadir was < 200 cells/mm3 with AIDS defining clinical condition in 27.2% of them." (PMID 36329104, 2022). "SIVmac239 with a disrupted YXXL motif by a ΔGY mutation did not deplete mucosal CD4 T cells when infecting rhesus macaques, but was still able to induce immune activation and progression to AIDS." (PMID 35323042, 2022). "CD4/CD8 ratio ≤ 0.4 was also associated with increased risk of some specific serious non-AIDS events, such as cardiovascular (1.89; 95%CI 1.19, 3.00) and non-AIDS defining malignancies (1.52; 95%CI 1.10, 2.12)." (PMID 35428209, 2022). "Chronic human immunodeficiency virus type 1 (HIV-1) infection typically results in the progressive loss of CD4+ T lymphocytes, and overactivation and functional exhaustion of CD8+ T lymphocytes, which can lead to acquired immunodeficiency syndrome (AIDS) if untreated." (PMID 35351857, 2022). "An increase in CD4 count decrease a 10% the probability of AIDS‐related mortality." (PMID 35916394, 2022).
AIDS (continued). "Despite being associated with moderately increased levels of chronic immune activation, this infection neither accelerated CD4+ T-cell depletion nor caused overt AIDS." (PMID 36713371, 2022). "Shingles, CD4, BMI, HB and TC were found linked to HIV/AIDS-related death." (PMID 34991536, 2022). "NHL is usually only seen in the late stages of AIDS where CD4+ counts are below 100 cells/mm3." (PMID 34586712, 2022). "Over 90% of C. neoformans meningitis cases were diagnosed in AIDS patients with CD4+ T cell count <100 cells/μl; however, the mechanism of cryptococcal meningitis in patients with normal immune functions remains unclear." (PMID 35720334, 2022). "This is different to other viral infections such as HIV, for which persistently low CD4/CD8 ratio is associated with worse outcome and increased risk of non-AIDS, or systemic diseases like sarcoidosis, for which lack of expansion and high ratios is advantageous." (PMID 35814752, 2022). "Progression of AIDS and rapid drop of CD4 count augment levels of inflammation." (PMID 35453518, 2022). "The CD4+ T-lymphocyte count was used as a surrogate marker for AIDS progression in our study." (PMID 35368687, 2022). "HIV-positive populations with RCC, in addition to having parallel symptoms, may exhibit some AIDS-related clinical manifestations, such as opportunistic infections and ADCs, especially in those who have low CD4+ T cell counts." (PMID 35433425, 2022). "A persistently low CD4/CD8 ratio was correlated with the risk of AIDS or non-AIDS defining cancer in PLWH efficiently treated by cART, such as Kaposi sarcoma, non-Hodgkin lymphoma, Hodgkin lymphoma, and lung cancer." (PMID 35873145, 2022). "The majority of aspergillosis cases in HIV/AIDS patients in the last 15 years have occurred in untreated patients, those noncompliant with antiretrovirals and patients with advanced immunosuppression, i.e., CD4 counts less than 50 cells/mm3." (PMID 36354898, 2022). "However, there are still 15–20% of AIDS patients with complete inhibition of virus replication after cART, and the CD4+ T-cell count cannot be restored to the normal level of uninfected people, a phenomenon termed immune non-response (INR)." (PMID 36195585, 2022). "Indeed, a series of studies indicated that several plasma biomarkers of systemic inflammation after ART initiation are potentially more predictive for future non-AIDS complications or CD4+ T cell recovery than cellular markers of immune activation." (PMID 35444646, 2022). "The hallmark of untreated infection includes persistently high viral load (VL), decline in CD4 T-lymphocyte (CD4TL) counts and systemic immune activation, ultimately leading to the development of acquired immunodeficiency syndrome (AIDS)." (PMID 36298774, 2022). "Human immunodeficiency virus (HIV) mainly attacks CD4+T lymphocytes and causes cellular immune deficiency, and patients with HIV infection may develop acquired immune deficiency syndrome (AIDS)." (PMID 36419079, 2022). "Typically, AIDS is defined as less than 200 cells/μL for CD4+ T cells." (PMID 36354458, 2022). "HIV progression (AIDS) may be associated with this increased risk of suicide through the direct effects of a high viral load on the brain and HAART, and a high level of CD4 was associated with decreased level of suicidal attempts." (PMID 36142061, 2022). "Death was largely caused by AIDS-related conditions and was associated with age > 40 years, CD4+ <100 cell/μL, and no ART use." (PMID 35359787, 2022). "Previous studies found that CM based on first-line ART could ameliorate symptoms and signs of AIDS, improve quality of life, increase CD4+ T cell counts, promote adaptive immunity, and prolong survival." (PMID 35126600, 2022). "On the other hand, the subsequent decline of CD4 counts leading to AIDS may be affected by these variations." (PMID 35271687, 2022).
AIDS (continued). "In addition, HIV-2-infected individuals have been shown to develop clinical AIDS at a higher CD4% compared with HIV-1-infected individuals." (PMID 36366545, 2022). "In terms of medical applications, genome editing using ZFNs entered phase I clinical trials to knockout the C-C chemokine receptor type 5 (CCR5) gene, a co-receptor expressed on CD4+ T lymphocytes, aiding the entry of human immunodeficiency virus to develop acquired immunodeficiency syndrome (AIDS)." (PMID 36429042, 2022). "However, 5.7% (54/945) of patients with available CD4 cell count values had a baseline count of <200, which classified them as having AIDS by the CDC." (PMID 35468087, 2022). "However, very few studies have attempted to assess the performance of the CD4/CD8 ratio in AIDS-related lymphomas in the immunotherapy era." (PMID 35873145, 2022). "Pathogenesis of HIV/AIDS involves several factors, not a single virus-controlled destruction of CD4+ T cells; among various pathogenic mechanisms there is autoimmunity directed against lymphocytes, platelets and peripheral nerves." (PMID 35335016, 2022). "The reduction in CD4+ T-cell counts, coupled with an increase in CD8+ T-cells, leads to an inversion of the CD4+:CD8+ ratio and typically predicts the non-acquired immunodeficiency syndrome (AIDS) morbidity." (PMID 35955721, 2022). "In addition, a small number of patients in the group with suppressed VL at baseline (7/521, 1.3%) also had a CD4 cell count that classified them as having AIDS." (PMID 35468087, 2022). "In the present study, results showed that there were 79% and 68% decrease in AIDS-related mortality risk with immediate ART and delayed ART, respectively, compared with late ART, whether in patients with high CD4+ cell counts or low counts." (PMID 34592916, 2021). "In addition, these patients usually present advanced AIDS disease with low CD4+ lymphocyte counts (median 98–133 cells/μL)." (PMID 34771697, 2021). "IMPORTANCE HIV-1 infection and subsequent depletion of CD4+ T cells result in AIDS." (PMID 34613803, 2021). "AIDS results from a prolonged HIV infection that depletes a patient’s CD4 count over time." (PMID 34094761, 2021). "Therefore, although it would have been interesting to examine the impact of viral load on surgical outcomes, we chose to rely on CD4-CC to determine the participants’ HIV/AIDS status." (PMID 34616598, 2021). "A large cohort study showed a lower CD4 count at the start of ART to be associated with death due to AIDS, renal failure, AIDS infection, non-AIDS malignancy and other causes, but not with death due to AIDS malignancies." (PMID 34886257, 2021). "Our observation strengthens these findings, in that a higher percentage of patients who died of HBV/HCV-associated causes had a CD4 count of more than 200 cells/mm3 at HIV diagnosis as well as at initiation of cART, compared to patients who died from AIDS-related conditions." (PMID 34886257, 2021). "When the CD4 count drops below 200 cells/μl, the patient will have progressed to AIDS." (PMID 34324280, 2021). "CD4 T cell loss and/or dysfunction are the most prominent features of HIV/AIDS." (PMID 34017335, 2021). "In this prospective study of HIV+ MSM undergoing a screening/treatment program for anal mucosa dysplasic lesions, the presence of ≥high-grade anal intraepithelial lesions were related to infection by HPV genotypes 11 16, 18, 53, 61 and 68, a low CD4 nadir and a history of AIDS." (PMID 33534790, 2021). "All of them separately analyzed ADC and NADC in people with previous AIDS or CD4 < 200/cells/μL." (PMID 33670229, 2021). "In our study, the two significant predictors of AIDS and mortality in the multivariable analysis were lower CD4 count at last paediatric care visit and having had an AIDS diagnosis in paediatric care (at median age 7 years), which themselves indicate suboptimal health outcomes in paediatric care." (PMID 33939876, 2021).
AIDS (continued). "AIDS patients (CD4 < 200) had the highest abundance of viral reads (excluding HIV-1 reads)." (PMID 33952659, 2021). "Patients with HIV/AIDS and low CD4 + T-cell counts should be monitored closely." (PMID 33492419, 2021). "The possible justification for this might be like the patients' CD4 count decreased stage of HIV/AIDS becomes advanced, and they manifest more typical signs of HIV infection." (PMID 34721902, 2021). "Risk factors for azole-resistant oropharyngeal candidosis in AIDS patients, such as a low CD4 count, prolonged or multiple courses of therapy, intermittent therapy, a low daily azole dose (<100 mg/day), and a high total cumulative azole dose, have been identified." (PMID 34356934, 2021). "If left untreated, HIV-infected individuals progress to acquired immunodeficiency syndrome (AIDS), which is characterized by increasing plasma viremia and corresponding depletion of CD4+ T cells through complex immune dysfunction including CD4+ T cell death and CD8+ T cell activation and expansion." (PMID 34578331, 2021). "Of the other potential factors, lower CD4 count at last paediatric care visit [adjusted hazard ratio (aHR) (95% CI) = 0.8 (0.7–1.0)/100 cells/μL increase, P = 0.03] and an AIDS diagnosis in paediatric care [aHR = 2.7 (1.4–5.5), P = 0.004] remained significant after adjustment for other factors." (PMID 33939876, 2021). "In HIV/AIDS, a compromised immune system with lower CD4 T-cell counts might waive the clinical symptoms and inflammatory responses, which suggests lymphocyte redistribution as an immunopathology leading to lymphopenia in COVID-19." (PMID 34646783, 2021). "This is likely because such children have advanced HIV-infection with severe symptoms like a very low CD4 cell count as well as rapid disease progression, with AIDS-defining illnesses like pneumocystis pneumonia, toxoplasmosis and ctyomegalo infections, among others." (PMID 33503074, 2021). "The transmission way of AIDS has a significant effect on CD4 counts." (PMID 33766121, 2021). "Our results demonstrate the urgent need to advocate early ART for improving survival of HIV/AIDS patients, whether with high or low CD4+ cell counts, especially for elders, males, and patients infected through blood transmission." (PMID 34592916, 2021). "Similarly, HCV coinfection is a major cause of non-AIDS-related morbidity and mortality in people living with HIV (PLWH) as it is associated with reduced or slower CD4+ T cell reconstitution after antiretroviral therapy (ART)." (PMID 34456931, 2021). "Therefore, modeling and analysis of factors affecting the number of CD4 cells in AIDS research is important." (PMID 33766121, 2021). "Nevertheless, despite the observed increase in the CD4 count during the gap, which seemed to have protected these patients from the risk of developing AIDS, we still found evidence of a higher risk of serious non-AIDS events in this group." (PMID 33953250, 2021). "HIV-infected individuals without antiretroviral therapy are clinically characterized by loss of CD4 T-cell and rise of plasma HIV RNA load, which could result in increased risks for opportunistic infections and development of AIDS and AIDS-related deaths." (PMID 34399785, 2021). "A decrease in CD4+ T-cells by HIV-1 infection leads to acquired immunodeficiency syndrome (AIDS)." (PMID 34071792, 2021). "One possible consequence of visiting hospitals less frequently during the COVID-19 outbreak is the frequent clinical deterioration of patients during the second half of 2020, as evidenced by an increased number of PLWH being admitted with advanced HIV/AIDS, lower CD4 counts and higher viral loads." (PMID 33925506, 2021). "Also, persons with clinical AIDS started ART later in comparison to persons with CD4 count < 200/mm3, with an increasing difference from low to high quantiles, at the 75th quantile, ART was initiated 2.6 (95% CI 1.8–3.5) times later." (PMID 34006927, 2021).